TAP1 (transporter 1, ATP binding cassette subfamily B member)
Diseases named in the same sentence as TAP1 in open-access papers (continued):
Sharing a sentence is not in itself a finding about the gene and the disease.
cancer (continued). "Of these genes, TAP2, B2M, IRF1, TAP1, HLA-A, HLA-B and HLA-C were formally and independently classed as CRC drivers, with strongest signals in MSI cancers, but also discovered in MSS cancers (for example, HLA-A and B2M)." (PMID 39112709, 2024). "Specifically, TAP1, TAP2, TAPBP, PSMB8, and CALR were significantly upregulated in 17, 14, 13, 15, and 15 distinct cancer types, respectively." (PMID 38297270, 2024). "We conclude that correlations between TAP1 expression and four specific lymphocyte populations (activated CD4+ T, CD8+ T, B, and NK cells) infiltration levels were evident in 12 types of cancer in which TAP1 has a protective role." (PMID 36759763, 2023). "The increased expression of TAP1, TAP2, Tapasin was also observed in colorectal CT26 cancer cells treated with 10 μM ACB-1801." (PMID 36458012, 2022). "In conclusion, our study demonstrates that TAP1(ABCB2) enhances the MEKi resistance in PDAC cells through transporting MEKi out of cells and promotes cancer stemness." (PMID 35806187, 2022). "Results showed MHC genes, including TAPBP, TAP1, and TAP2, were highly positively correlated with FANCE in most cancers." (PMID 36685883, 2022). "MHC class I presentation of antigens on cancer cells triggers recognition by cytotoxic T-cells and destruction of the cancer cell, making TAP1 and TAPBP critical for anti-cancer immunosurveillance." (PMID 36303210, 2022). "Here, the intratumoral expression of TAP1 and TAP2 showed higher clustering with increasing M1 population in several cancer types." (PMID 34078917, 2021). "Thus, TAP1 may be a new therapeutic target for OC and other kinds of cancers." (PMID 34957213, 2021). "Overexpression of TAP1 gene in cancer patient compared to normal tissue was most in stage 2 for LUAD (p = 3.37e-09) and LIHC (p = 2.97e-08) cancer, stage 2 (p = 1.62e-12) and stage 4 (p = 1.08e-03) were among the highest for BRCA." (PMID 34047812, 2021). "Lastly, we figured out the genes that positively correlated with the TAP1 gene in BRCA, LIHC, LUAD, and OV cancer by using the R2 genomics analysis and visualization platform." (PMID 34047812, 2021). "The GEPIA2 tool was used to look into the expression of the TAP1 gene, where the expression levels for LIHC and OV cancers were significantly higher than the normal tissues." (PMID 34047812, 2021). "Therefore, the study utilized various data from different databases and focuses on the expression pattern of TAP1 in various cancer, analyzed the gene for determine different clinical features, determined the copy number and amplification frequency to evaluate the role of gene in cancer." (PMID 34047812, 2021). "Taken together, these results indicate that chemotherapeutic agents promote translocation of HLA-G to the cancer cell surface by downregulating DMNT1 expression and TAP-1 promoter demethylation." (PMID 34663641, 2021). "We used the PLK1 inhibitor (BI2536) to treat cancer cell lines and compared expression levels of MHC class I (HLA-A, HLA-B, HLA-C, B2M, and TAP1 genes and their protein products) between the pre- and post- treated cell lines." (PMID 30631355, 2018). "Given that TAP1 plays an important role in immune response and the polymorphisms of this gene may result in the conformational and functional change, and thus may affect individual’s susceptibility to HPV infection and subsequently the HPV-associated cancer development." (PMID 26205887, 2015). "On Western blot analysis with lysates from cultured cell lines, HLA-HC, β2 microglobulin, tapasin, TAP-1, TAP-2, LMP-7, and LMP-10 expressions differed among the cancer cell lines." (PMID 22134332, 2012). "HLA-HC, β2 microglobulin, tapasin, TAP-1, and TAP-2 were detected on cell membranes and cytoplasm in both cancer cells and normal mucosa." (PMID 22134332, 2012).
cancer (continued). "One notable aspect of our results is the prominent difference in the frequency of TAP1 and TAP2 cancer cell downregulation in NSCLC, as well as their dissimilar impact on surface antigenic peptide abundance and role in protection of cancer cells from T-cell attack." (PMID 40091029, 2025). "Virtually no Annexin V positivity was detected in preparations containing only cancer cells with or without TAP1/2 silencing or after pre-incubation with IFNγ ± TNFα (e.g. (T) 1: (E) 0)." (PMID 40091029, 2025). "Patients with tumors containing low cancer cell TAP1 showed comparable OS with those without TAP1 downregulation regardless of the treatment type." (PMID 40091029, 2025). "An association of NOTCH1 loss of function mutation with TAP1 dependency was present but of unclear significance given that the TAP1 gene product's role in antigen presentation is not predicted to impact cancer cell line viability or growth in standard culture." (PMID 37997254, 2024). "TAP1 was abundantly expressed across all cell clusters, ULBP2 was primarily expressed in T cells, CXCL1 was mainly expressed in CAFs, myeloid cells, normal epithelial cells, and cancer epithelial cells." (PMID 39020010, 2024). "Importantly, TGF β1 targets the APM molecules in cancer cells by downregulating the H2 complex (MHC I in mouse), B2m, Tap1, and Tap2 shown in an in vitro model of CCK168 squamous cell cancer cells." (PMID 38067396, 2023). "In our study, patients with BLCA, BRCA, and SKCM and high TAP1 expression all exhibited better prognosis, consistent with the cohort analysis; h Especially, we also demonstrated that BLCA and SKCM cancer patients with higher TAP1 expression showed more sensitivity of ICI therapy in our study." (PMID 36759763, 2023). "Cancer cell lines expressed relatively low levels of TAP1 transcripts, but were rendered completely negative by CRISPR-CAS9 technology." (PMID 34142235, 2022). "We speculate that an increase of cell surface expression of HLA-G on chemotherapy-treated cancer cells is mediated by downregulation of DMNT1 and epigenetic regulation of the TAP-1 promoter." (PMID 34663641, 2021). "• This study reported a significant negative correlation for TAP1 gene expression and the survival rate in different cancer types." (PMID 34047812, 2021). "Recent studies have reported the function of TAP1 in some cancers, but the role of TAP1 in immune infiltration, immunotherapy, and metastasis across various cancers has not been reported thus far." (PMID 34957213, 2021). "TAP-1 and TAP-2 down-regulation in general will lead to a reduced efficiency in antigen presentation and immune-responses and is considered as an important mechanism of cancer immune-escape." (PMID 20865050, 2010). "In samples containing both A549 and CD8+ T-cells, the downregulation of TAP1 induced no detectable changes in T-cell killing under control/unstimulated condition, and only partially increased the cancer cell viability in samples pre-incubated with proinflammatory cytokines." (PMID 40091029, 2025). "owever, TAP1 was not a favorable factor for immune therapy responses in all cancer types." (PMID 36759763, 2023). "Therefore, there is no consistent relationship between TAP1 expression and patient prognosis for different cancer types." (PMID 36774490, 2023). "In addition, CCNA2 could positively regulate TAP1, TAP2, CD276, MICB, PVR, and ULBP1 in almost all the cancer types." (PMID 35401923, 2022). "However, the effect of TAP1 on immune infiltration, immunotherapy, and metastasis in different cancers has not been reported till date." (PMID 34957213, 2021). "Most tumors showed comparable levels of TAP1 and TAP2 protein in both CK-positive cancer cells and in CK-negative (non-malignant) stromal cells." (PMID 40091029, 2025).
cancer (continued). "When the expression of MHC I pathway genes was analyzed by qPCR, we found reductions in transcripts of TAP1, TAP2, and ERAP1 genes (other MHC I pathway genes were not examined), which was consistent with our earlier studies with other cancers." (PMID 39354629, 2024). "Moreover, the expression levels of TAP1 and TAP2, another two molecules essential for MHC-I-mediated antigen presentation, are also relatively higher in responders than non-responders in CRC and many other cancers." (PMID 36551849, 2022).
infection (49 papers, 2005 to 2026). The state of being infected such as from the introduction of a foreign agent such as serum, vaccine, antigenic substance or organism. "To confirm varying TAP-dependencies of HLA-B cell surface expression, we examined TAP1-mediated cell surface induction of HLA-B molecules following further infection of selected SK19-HLA-B cell lines with a TAP1-encoding retrovirus." (PMID 29995954, 2018). "Over the course of infection TAP1-null mice showed significantly more weight loss as compared to WT B6 mice." (PMID 28151989, 2017). "Despite robust development of neutralizing antibodies infection in TAP1-null mice and beige mice is associated with relatively high mortality." (PMID 28151989, 2017). "Regardless, mice deficient in CD8+ T cells or in the so-called transporter associated with antigen processing (TAP-1) protein, while more susceptible to infection with T. gondii, often survive 30–40 days post-infection." (PMID 20865117, 2010). "According to the results of our research, compared with susceptible individuals, the high expression of the TAP1 gene among resistant piglets might benefit the individuals to prevent E. Coli F18 infection." (PMID 24955792, 2014). "We also observed the upregulation of DEGs related to antigen presentation such as Tap1 and Tap2, in particular during infection with NF1_LV, suggesting the activation of the adaptive immune system." (PMID 39735262, 2024). "Host cells, via increasing the expression of HSP70/90, PA28, TAP, and TAP1/2 genes, deploy chaperones, immunoproteasomes and transporters to limit infection, through promoting antigen processing and presentation." (PMID 30428922, 2018). "On day 12 days post-infection leukocytes from the brains of TAP1-null mice were quantified with uninfected mouse brains as controls." (PMID 28151989, 2017). "We also observed that on day 12 post-infection about 30% of infected TAP1-null show presence of virus in the brain." (PMID 28151989, 2017). "We speculated that high expression of the TAP1 gene might confer resistance against the E. coli F18, the G729A mutation had a significant effect on the mRNA expression, and individuals with the GG genotype possessed a stronger ability to resist the E. coli F18 infection." (PMID 24955792, 2014). "Other genes involved in immune response which were up regulated in all time point of infection were Mpa 21, Mx2, Mx1 Phf11, Tgtp, B2 m and Tap1." (PMID 21371334, 2011). "Calculations based on the threshold cycle number indicated that the abundance of human TAP1 mRNA was equal to mouse TAP1 mRNA 4 and 8 h after infection, but decreased to 2% of endogenous mouse TAP1 mRNA by 24 h after infection." (PMID 16389301, 2005). "Human TAP1 mRNA levels were quantified with real-time RT-PCR in splenocytes from mice 4, 8, and 24 h after intraperitoneal (i.p.)infection." (PMID 16389301, 2005). "Similarly, HW infection suppresses select type I interferon-related genes (TAP1 and IRF7) in the intestine, but this effect is reversed by CoV coinfection, suggesting a shared IFN-driven antiviral mechanism." (PMID 41268552, 2025). "Moreover, genes involved in antigen presentation (e.g., Fcgr1, Tap1, and Cd40) gradually increased over the course of infection in WT microglia, whereas in Mavs−/− microglia they remained unchanged." (PMID 39425188, 2024). "Besides, the transporter associated with antigen processing (TAP, TAP1, TAP2) and most MHCs showed a decrease in expression at 28, 38 h post-YC-2020 infection, with a stronger downtrend than the JXA1 group." (PMID 36338035, 2022). "Notably, we found that NK cells were significantly less effective at killing Tap1-/- cells in vivo in Ifnar1ΔNKp46 mice than in Ifnar1fl/fl mice following ECTV infection." (PMID 34015056, 2021). "The majority of genes (CTNNB1, MARCO, STAT5a/b, TAP1, and TAP2) that regulate proliferation and differentiation of immune cells showed a differential higher expression in KO and SP-A variants in response to infection." (PMID 32670284, 2020).
infection (continued). "Analysis of the vessel data revealed several proteins related to the acute-phase response to infection (Hp, Hpx, Serpina3n, Fga/b, Igfbp7, Cfh, and C4b), antigen presentation (Tap1, Tap2, Tapbp, H2-D1, and H2-Q10), and interferon response (Igtp, Gbp2, Irgm1, and Iigp1)." (PMID 32843537, 2020). "Similarly, expression of several genes in the canonical IFN signaling pathway, including Ifng, Jak2, Stat1, Stat2, Socs1, Irf1, Irf9, Tap1, Ifitm1, Psmb8, Ifi35, Gas1 and Fit3 were up-regulated during infection by the mutant strain." (PMID 25201772, 2014). "From the results of three independent experiments, we found that the inability to undergo autophagy during infection led to higher expression of many pro-inflammatory genes as compared to autophagy-competent cells, including established ISGs, such as Psmb10, Cd274, Cxcl10, Irf1 and Tap1." (PMID 29748576, 2018). "Importantly, infection with Ad5-IFNγ induces TAP1 and TAP2 expression in the RM-1 cell lines." (PMID 23056548, 2012). "The MHC-I pathway-related genes (TNF, HSP70, TAP1/2, and TAPBP) were upregulated after infection in the head kidney and spleen compared to those of the MHC-II pathway." (PMID 36835242, 2023). "RNA-seq showed that the expression of ACOD1 and its downstream genes (HMOX1, TNFAIP3, TAP1, ATF3, and NRF2) was significantly upregulated post infection." (PMID 37256871, 2023). "Among the three peptide transporters identified, an increased expression was observed in TAP1 and TAP2 genes in cells infected with the mutant virus, while a higher expression was recorded for TAPBP during infection with the WT virus." (PMID 37513744, 2023). "In M2 macrophages, genes associated with an inflammatory profile were more extensively upregulated by infection with rBCG-LTAK63, compared to infection with BCG, including the TAP1 and GBP1 genes, which are both part of the IFN signaling pathway." (PMID 35746439, 2022). "Both, GMCSF- and FLT3L-BMDCs responded to mOVA2 infection with type I IFN activation signatures, e.g. induction of p-STAT1(Y701), STAT1, TAP1 and ISG15." (PMID 31988324, 2020). "On the other hand, Tap1−/− mice succumb to infection faster than Cd8−/− mice, and CD4+ T cells and NK lymphocytes from Tap1−/− mice produce reduced amounts of IFN-γ, indicating that TAP deficiency affects both acute and chronic phases of Toxoplasma infection." (PMID 30891027, 2019). "However, in the presence of the strong Irf-7-mediated response associated with infection of 14M1.4 cells, we observed a reciprocal regulation of genes related to MHCI- and MHCII-restricted antigen presentation, with elevated levels of transcripts for MHCI, TAP1 and tapasin." (PMID 20300600, 2010). "In addition, PARP12, TAP1, CMPK2 and ADAR, which are crucial to restrict RNA virus replication, e.g. DENV、HIV、ZIKV, also upregulated in the early stages of HuB20 infection, indicating multiple antiviral responses was involved in this stage." (PMID 36544767, 2022). "For example, we detected the effect of TAP1 on HSV-1 (a kind of enveloped DNA virus) and adenovirus (a kind of nonenveloped DNA virus), and results showed that TAP1 overexpression significantly inhibited their infection in a dose-dependent manner." (PMID 33925089, 2021). "However, in response to infection, male mice exhibited higher expression levels of CDKN1B, and CTNNB1 (KO, 1A3), TCF4 (1A0, 6A2), TAP1, and TAP2, (1A0), CDKN1A, (1A3, 6A2), MARCO, and MMP12 (1A3), CCND1, CDK2, IRF and MYC (6A2) compared to females." (PMID 32670284, 2020). "Morbidity in infected TAP1-null mice became apparent from day 10–12 post-infection with significantly higher clinical scores, unlike in TCRβ-null mice in whom clinical score started going up earlier." (PMID 28151989, 2017). "To ensure that antigen presentation in infected cells occurred via the conventional endogenous processing pathway, we measured antigen presentation following infection of mice lacking TAP1, a vital component of this pathway." (PMID 26107264, 2015).
infection (continued). "After IFN-γ stimulation, the infection did not alter the proteasome immunosubunits, PA28β, TAP1 and MHC class I protein levels, indicating that T. cruzi does not degrade these proteins." (PMID 24752321, 2014). "mRNA expression measured at various time points (1, 3, 12, 24, 36 and 48 hpi) by real-time RT-PCR showed that infection of PK-15 cells with CSFV at either a MOI of 0.1 or 1.0, resulted in down-regulation of seven immune response genes, namely SLA-2, TAP1, SLA-DR, Ii, CD40, CD80, CD86." (PMID 22925563, 2012). "tularensis LVS-infection; a significant upregulation of genes involved in RAS pathway including Ccl2, Nfkb, p38 Mapk, Ras, Stat1, Stat3 and Tnf-α; and an upregulated expression of IFN-γ pathway genes such as Bak, Bax, Ifit, Ifn-γ, Irf, Isg, Oas1, Psmb8, Ptpn2, Stat and Tap1." (PMID 37266014, 2023). "The finding that the preferential killing of Tap1-/- cells in ECTV-infected Ifnar1ΔNKp46 mice was significantly reduced highlights the importance of the crosstalk among innate immune cells in the dLN where both iMOs and NK cells migrate to upon infection, and where iMOs express IFN-I." (PMID 34015056, 2021). "Moreover, an increase in TAP1 and BCAP31 mRNA was also partly observed in infected cells treated with miR-346 inhibitor, suggesting a role of miR-346 in counteracting the upregulation of these genes during infection." (PMID 29867904, 2018). "Prior to infection, investigation of the expression of key macrophage differentiation markers indicated that (unstimulated) iPSDMs expressed low to very low levels (0.1–5 counts per million (c.p.m.)) of M1 markers (CXCL10, CXCL11 and TAP1) and also modest levels (10–1,000 c.p.m)." (PMID 28440293, 2017). "Furthermore, increased levels of TAP-transporters (TAP1, TAP2), MHC I components B2M and HLAs, together with the ER chaperons calreticulin (CALR) and calnexin (CALN), and aminopeptidases ERAP1 and ERAP2 indicated upregulation of MHC I dependent antigen presentation with progressing infection." (PMID 37112941, 2023).
immune diseases (5 papers, 2014 to 2024). "The TAP1 expression level was influenced not only by TAP1 I333V gene polymorphism but also by other genetic and environmental factors, such as ethnicity, inflammation state and other immune system diseases." (PMID 24655325, 2014). "Genes involved in antigen processing and presentation, such as transporter 1 (Tap1), which is involved in antigen processing, and proteasome subunit‐β type‐9 (Psmb9), have been shown to play potential roles in a variety of immune diseases." (PMID 39295096, 2024). "Several male DEGs have been implicated in immune diseases, particularly genes of the MHC class I and II regulation (Tap1, Ciita, H2-Q4, H2-T-ps, H2-T10 and H2-T23)." (PMID 36982971, 2023).
adenocarcinoma (1 paper, 2025). A common cancer characterized by the presence of malignant glandular cells. "In the analysis of clinicopathologic variables, cases with low TAP1 showed no consistent associations and TAP2 downregulation was more frequent in tumors with squamous cell histology than in adenocarcinomas." (PMID 40091029, 2025).
infectious disease (1 paper, 2021). A disorder directly resulting from the presence and activity of a microbial, viral, or parasitic agent in humans. "In conclusion, this study enriched our understanding of the broadly antiviral function of TAP1 by regulating innate immunity and provided insights into developing novel antiviral strategies against a variety of emerging infectious diseases." (PMID 33925089, 2021).